MAPK13 (mitogen-activated protein kinase 13)
Diseases named in the same sentence as MAPK13 in open-access papers (continued):
Sharing a sentence is not in itself a finding about the gene and the disease.
triple-negative breast carcinoma (1 paper, 2017). An invasive breast carcinoma which is negative for expression of estrogen receptor (ER), progesterone receptor (PR), and human epidermal growth factor receptor 2 (HER2). "Silencing of MAPK13 has also been shown to promote cell growth in triple-negative breast cancer." (PMID 29215599, 2017).
tumor (25 papers, 2015 to 2025). "Epigenetic alterations of the MAPK13 gene were also found in primary cutaneous melanoma, associated with tumor growth." (PMID 33923030, 2021). "For example, MAPK13 (mitogen-activated protein kinase 13) has been found in gynaecological cancer to be preferentially expressed in cancer stem cells and it is implicated in the tumour-initiation." (PMID 37875584, 2023). "According to previous studies, MAPK13 plays an important regulatory role in inflammatory response, cell growth, and tumor formation and progression." (PMID 39558374, 2024). "In summary, we employed WGCNA to identify gene modules corresponding to the NOR-CIN-CC transition and discovered that CARMN functions as a hub gene and tumor suppressor in CC by modulating both ROS/Akt/mTOR and MAPK13-mediated MAPK signaling pathways." (PMID 39558374, 2024). "Among the various MAPK family proteins, MAPK13 has been shown to contribute to tumor progression and inflammatory responses." (PMID 37599001, 2023). "Our findings therefore highlight MAPK13 as a promising target for combination therapy with rapamycin to overcome the limited tumor suppression efficacy of rapamycin." (PMID 37599001, 2023). "Here, we identified MAPK13 as a target gene regulated by mTORC1-dependent m6A regulation and as another key factor that potentially limits rapamycin’s tumor-suppressive effects." (PMID 37599001, 2023). "While p38α/MAPK14 isoform has been most extensively studied, p38δ/MAPK13 has recently emerged as a potential drug target because of its roles in stress responses, cytokine production, and tumor development." (PMID 37599001, 2023). "In this study, we report that a mitogen-activated protein kinase (MAPK)/p38 isoform, MAPK13/p38δ, is a downstream target of the mTORC1–m6A RNA modification pathway, which likely contributes to the limited tumor-suppressive effects of rapamycin." (PMID 37599001, 2023). "MAPK13 gene knockdown using siRNA reduced the ALDHhigh population and abrogated tumor-initiating ability." (PMID 33923030, 2021). "Among these genes, four genes (TIMP1, MAPK13, MAPKAPK2 and MAPKAPK3) are known to regulate cell proliferation, and MMP2 and MMP9 control tumour-associated tissue remodelling; PIK3CD is involved in the immune response, and AKT2 regulates tumourigenesis." (PMID 32999349, 2020). "Gene knock down of MAPK13 significantly decreased tumor-initiation ability and sphere-forming ability, thus MAPK13 has a role in the maintenance of CSCs/CICs." (PMID 28415561, 2017). "Importantly, elevated levels of VEGFB, PDGFRA, MAPK13, and HGF have been previously linked to poor prognosis and aggressive tumor behavior in HCC." (PMID 41002582, 2025). "Together, these findings indicate that MAPK13 induction by rapamycin limits the tumor-suppressive effects of rapamycin, and the combinatory treatment of rapamycin with MAPK13 inhibitor can be more effective in impairing tumor growth compared with the rapamycin monotherapy." (PMID 37599001, 2023). "Consequently, inhibition of MAPK13 activity in conjunction with rapamycin offers the most effective tumor suppression (right)." (PMID 37599001, 2023). "Previous studies on cancer stem-like cells (CSCs) discovered that knock down of MAPK13 greatly abrogated CSCs tumor-initiating ability, indicating that MAPK13 might play a role in tumor progression." (PMID 32299063, 2020). "It has been reported to act as a tumor suppressor in HCC, increasing sorafenib sensitivity through the downregulation of MAPK13 and modulating the MEK/ERK and ATF2 signaling pathways." (PMID 39906666, 2024). "It was also found that ERK pathway was enriched in tumor specimen after receiving chemotherapy, several ERK pathway component genes expression elevated in KEGG and REACTOME GSEA results, such as MAPK10, MAPK13, MAPK11 and MAPKAPK3." (PMID 29296238, 2017).
cancer (18 papers, 2017 to 2025). A tumor composed of atypical neoplastic, often pleomorphic cells that invade other tissues. "Together, our data indicate that rapamycin-mediated MAPK13 mRNA stabilization underlies drug resistance, and it should be considered as a promising therapeutic target to sensitize cancer cells to rapamycin." (PMID 37599001, 2023). "p38 mitogen-activated protein kinase (MAPK) signaling including p38α MAPK (MAPK14), p38β (MAPK11), p38γ (MAPK12) and p38δ (MAPK13) is associated with the development and progression of several types of cancer." (PMID 32894113, 2020). "Similarly, hypermethylation of SHISA3, KCNA3, NPY, and hypomethylation of NUMB, BST2, MAPK13 promoters, which have previously been implicated in other cancers, robustly separate normal and GBC-OSCC samples." (PMID 37245006, 2023). "MAPK13, also known as p38δ, possesses a basilic function in the oncogenesis and cancer development, including proliferation, EMT, invasion, metastasis." (PMID 39558374, 2024). "Even though the single treatment of rapamycin or MAPK13 knockdown reduced the proliferation of mTORC1-hyperactive cancer cells including LAM 621-101, UMB1949, and MCF7, rapamycin was more effective in cell growth suppression when MAPK13 was depleted." (PMID 37599001, 2023). "Here, we report that m6A modification of mitogen-activated protein kinase 13 (MAPK13) mRNA determines the sensitivity of cancer cells to the mechanistic target of rapamycin complex 1 (mTORC1)-targeting agent rapamycin." (PMID 37599001, 2023). "MAPK13 activation is involved in a wide variety of cellular processes such as proliferation, differentiation, transcription regulation and cancer development." (PMID 32299063, 2020). "In our study, the modular protein interaction networks evidenced MAPK13, a target associated with the PANDAR ncRNA of relevance to therapy because aberrantly expressed across various cancers." (PMID 30485296, 2018). "Thus, we decided to further study MAPK13 based on its dramatic and consistent induction in all conditions across diverse cancer cells." (PMID 37599001, 2023). "In view of the pro-oncogenic role of these proteins, it is noteworthy, that G6PD, MAPK13, PNCK, SLC16A3, and SLC2A1 are among the candidate cancer genes identified by forward genetic screens in mice." (PMID 33427197, 2021). "This included genes like, PIK3R2, PIK3CA, BIRC2 and ZBTB14 with implications in cancer that were over-expressed with FC above ≥10 in OS-DW in comparison to OS-R; while, expression of WNT5A, PIK3CB, ACVR1, MAPK13 and GBX2 were significantly reduced." (PMID 31690262, 2019). "Among the differentially expressed genes in metastatic samples, we found 7 of 30 genes (MAPK13, XIAP, AHR, SPN, TER1, EMP2, NDUFC2) were cancer-related." (PMID 28009993, 2017). "Among the differentially expressed genes in primary samples, 7 of 39 genes (VHL, GNE, POLH, MAPK13, NOP14, INADL, CDC5L) were reported to be cancer-related in the literature." (PMID 28009993, 2017). "In present study, higher expression of MAPK13 and MAPK14 were correlated with a better prognosis, which led to patients more sensitive to the chemotherapy and prolong the survival time of cancer patients." (PMID 28852147, 2017).
infection (3 papers, 2021 to 2024). The state of being infected such as from the introduction of a foreign agent such as serum, vaccine, antigenic substance or organism. "Several MAPK encoding genes, such as MAPK11, MAPK12, and MAPK13, were significantly up-regulated under HN10 infection and MAPK10 was significantly up-regulated under JDm10 infection." (PMID 35893682, 2022).
bacterial infection (1 paper, 2018). "Our analysis revealed downregulation of miRNA-150 during bacterial infection may exert broad effects on metabolism (SLCA2A3/GLUT3), cytokine regulation (SOCS1), and cell signaling pathways (MAPK13, IPO8, ACVR1B, RNF146) consistent with the host response to bacterial infection." (PMID 30619110, 2018).
MAPK13 also shares sentences with these, for which no sentence is quoted: Alzheimer disease (1 paper); cardiomyopathy (1); cardiovascular diseases (1); colorectal cancer (1); dementia (1); esophageal squamous cell carcinoma (1); gastric cancer (1); glioblastoma (1); influenza (1); injury (1); left ventricular hypertrophy (1); lung carcinoma (1); mesothelioma (1); ovarian carcinoma (1); ovary tumor (1); prostate carcinoma (1); renal angiomyolipoma (1); respiratory diseases (1); rheumatoid arthritis (1).